ERVFRD-1 (endogenous retrovirus group FRD member 1, envelope)
Description:
This endogenous retroviral envelope protein has retained its original fusogenic properties and participates in trophoblast fusion and the formation of a syncytium during placenta morphogenesis. The interaction with MFSD2A is apparently important for this process. Endogenous envelope proteins may have kept, lost or modified their original function during evolution but this one can still make pseudotypes with MLV, HIV-1 or SIV-1 virions and confer infectivity. Retroviral envelope proteins mediate receptor recognition and membrane fusion during early infection. The surface protein mediates receptor recognition, while the transmembrane protein anchors the envelope heterodimer to the viral membrane through one transmembrane domain. The other hydrophobic domain, called fusion peptide, mediates fusion of the viral membrane with the target cell membrane.
Synonyms: ERVFRDE1; HERV-W/FRD; HERV-FRD; envFRD; syncytin-2; GLLL6191; UNQ6191
Tractability: Antibody: UniProt places it where antibodies can reach, with high confidence; UniProt predicts a signal peptide or a membrane-spanning region; its Gene Ontology location is reachable by antibodies, with medium confidence.
Gene: Protein-coding gene on chromosome 6 (11,102,324 to 11,111,845, reverse strand). Ensembl gene ENSG00000244476.
Subcellular location: Virion; Cell membrane (Surface protein); Cell membrane (Transmembrane protein)
Subcellular location (Human Protein Atlas): Actin filaments; Plasma membrane; Cytosol; Nucleoplasm
Gene Ontology:
Molecular function: protein binding
Biological process: myoblast fusion; negative regulation of syncytium formation by plasma membrane fusion; syncytium formation by plasma membrane fusion
Cellular component: plasma membrane
Genetic constraint (gnomAD): Loss-of-function variants: 33 observed, 46.1 expected, observed/expected ratio (o/e) 0.72, 90% interval 0.54 to 0.96. The upper end of that interval is the gene's LOEUF score, 0.96, which puts it in group 4 of 6, group 1 being the genes least tolerant of losing a copy. Missense variants: 568 observed, 690.62 expected, observed/expected ratio (o/e) 0.82, 90% interval 0.77 to 0.88. Synonymous variants: 239 observed, 256.7 expected, observed/expected ratio (o/e) 0.93, 90% interval 0.84 to 1.04.
Homologues: Orthologues: chimpanzee ERVFRD-1 (99% identical), macaque ERVFRD-1 (95% identical), mouse Gm27179 (33% identical), mouse Synb (33% identical), rat Synb (32% identical), mouse Syna (31% identical), rat Ervfrd-1 (31% identical), rabbit ORY1 (25% identical). Paralogues in human: ERVW-1 (19% identical), ERVV-2 (9% identical), ERVV-1 (9% identical), ERV3-1 (9% identical), ERVMER34-1 (8% identical).
Diseases named in the same sentence as ERVFRD-1 in open-access papers:
ERVFRD-1 is named in the same sentence as 33 diseases in open-access papers, as found by Europe PMC text mining. Sharing a sentence is not in itself a finding about the gene and the disease. The quoted sentences say what the papers report.
acute myeloid leukemia (1 paper, 2022). Acute myeloid leukemia (AML) is a group of neoplasms arising from precursor cells committed to the myeloid cell-line differentiation. "Nevertheless, we noticed that syncytin‐1 (ERVW‐1) and syncytin‐2 (ERVFRD‐1) were activated in acute myeloid leukemia (LAML)." (PMID 34318590, 2022).
ZIKV infection (1 paper, 2023). "We observed a down-regulated expression of GCM1, OVOL1, ERVW-1, and ERVFRD-1 in hTSCs following ZIKV infection." (PMID 37684223, 2023).
cancer (9 papers, 2012 to 2026). A tumor composed of atypical neoplastic, often pleomorphic cells that invade other tissues. "Moreover, increased expression of ERVFRD-1 in cancers from the Cancer Genome Atlas (TCGA) with ERVFRD-1 fusions suggested that ERVFRD-1 promoted tumor growth by inhibiting the anti-tumor immune response of the host mice." (PMID 37780849, 2023). "The putative driver fusion (MYB–PCCA–NFIB) and the enhancer hijacking-like mechanism (HIST1H2AG–NonGenic–ERVFRD-1) shed new light on the role of complex SVs and splicing in cancer transcriptomics." (PMID 34811492, 2021).
tumor (6 papers, 2012 to 2023). "Additionally, we investigated the correlation between ERVFRD-1 expression and immune biomarkers, including immune modulators and tumor mutational burden (TMB)." (PMID 37780849, 2023). "Differential analysis and functional annotation using GO, KEGG, GSEA analysis revealed significant involvement of ERVFRD-1 in tumor immunoregulation: a close relation to the infiltration levels of mast cells and Treg cell (P < 0.001) and occurrence with a variety of immune markers." (PMID 37780849, 2023).
ERVFRD-1 also shares sentences with these, for which no sentence is quoted: preeclampsia (5 papers); COVID-19 (2); glioblastoma (2); infection (2); lupus (2); breast carcinoma (1); celiac disease (1); Clear Cell Renal Cell Carcinoma (1); colon cancer (1); Crohn disease (1); Diarrhea (1); endometrial carcinoma (1); endometrial polyp (1); endometriosis (1); Ewing sarcoma (1); germ cell tumor (1); hematological cancer (1); Hodgkins lymphoma (1); hyperplasia (1); Infertility (1); irritable bowel syndrome (1); melanoma (1); Miscarriage (1); myeloma (1); non-Hodgkin lymphoma (1); seminoma (1); testicular tumor (1); trisomy 21 (1); ulcerative colitis (1).